MAP4K4 (mitogen-activated protein kinase kinase kinase kinase 4)
Diseases named in the same sentence as MAP4K4 in open-access papers (continued):
Sharing a sentence is not in itself a finding about the gene and the disease.
cancer (continued). "MAP4K4 is overexpressed in many human cancer cell lines and tumors compared to normal tissue." (PMID 37190200, 2023). "Increasing evidence places MAP4K4 as a pro-metastatic regulator, inducing cancer cell migration." (PMID 37369604, 2023). "Furthermore, the knockdown of MAP4K4 by small interfering RNA inhibits the tumor cell migration and invasion of various cancer types and malignant melanoma." (PMID 37190200, 2023). "Is MAP4K4 ready for the main stage as a cancer therapy target?" (PMID 37223681, 2023). "MAP4K4 is overexpressed in many human cancers compared to normal tissues." (PMID 37190200, 2023). "Down regulation of MAP4K4 inhibited cancer cell adhesion, migration, and invasion." (PMID 36922678, 2023). "Recent research has shown that MAP4K4 plays a role in cancer development and its inhibition may be a novel treatment strategy for several types of cancer." (PMID 37223681, 2023). "MAP4K4 knock-down reduced the adhesive properties of cancer cells." (PMID 36922678, 2023). "It is important to consider some caveats about the potential use of MAP4K4 inhibition as a therapeutic agent in cancer, because MAP4K4 has a role in multiple fundamental signaling systems, including NFκB activation, regulation of small GTPases and the Hippo cascade." (PMID 37223681, 2023). "MAP4K4, a member of Ste20, plays an important role in various pathologies, including cancer." (PMID 36292671, 2022). "The knowledge of MAP4K4 in cancer is minimal, but increasing evidence suggests its role in cancer and might act as a new actionable target for cancer therapy." (PMID 36292671, 2022). "In-depth analysis of MAP4K4 functions in physiological and non-cancer pathological processes could thus reveal molecular mechanisms of MAP4K4 control of cellular processes that – when de-regulated - could contribute to tumorigenesis." (PMID 36568222, 2022). "Overexpression of MAP4K4 is detected in numerous human cancers." (PMID 35679904, 2022). "It is suggested that MAP4K4 might function as a cancer promoter via specific downstream target(s) in an organ-specific manner." (PMID 34511598, 2021). "However, in cancer cells, inhibition of MAP4K4 has been shown to prevent oncogenic properties, including cell migration." (PMID 34511598, 2021). "Several studies found MAP4K4 as a therapeutic target in cancer." (PMID 35071229, 2021). "The TNFα is known to induce inflammation and cancer; however, whether TNFα-induced MAP4K4 promotes cancer directly or indirectly is unclear." (PMID 34511598, 2021). "In the case of MAP4K4, the dephosphorylated state contributes to the growth of the cancer cell." (PMID 31913126, 2020). "To extend these observations beyond the HEK TER cells, we generated a MAP4K4 knockdown gene expression signature and assessed this signature across a large collection of cancer cell lines from the Cancer Cell Line Encyclopedia (CCLE) by performing ssGSEA analysis." (PMID 31913126, 2020). "The overexpression of MAP4K4 promotes cancer progression or metastasis." (PMID 31992202, 2020). "While the results shown here bear solely on cell survival, the demonstrated lack of a confounding effect on tumour cell killing by DOX gives obvious credence to further exploration of MAP4K4 inhibitors in these further aspects of cancer therapeutics, beyond just cardioprotection." (PMID 32694738, 2020). "Several studies have supported the clinical significance of MAP4K4 in cancer." (PMID 31570734, 2019). "Another MAP4K member, MAP4K4/HGK, induces cell migration and promotes cancer metastasis." (PMID 31640697, 2019). "This study suggests a MAP4K4 inhibitor could potentially serve as a meaningful adjuvant for this chemotherapy-resistant fatal cancer." (PMID 31570734, 2019). "MAP4K4 a serine/threonine kinase plays significant role in immunity, inflammation, metabolic and cardiovascular diseases and have been recognized as actionable cancer therapeutic target." (PMID 30644396, 2019).
cancer (continued). "For these reasons, inhibition of MAP4K4 has been proposed as a treatment for the other common cancer types, and may have a therapeutic role in a wide variety of cancers." (PMID 31570734, 2019). "One may speculate that treating patients who have cancer with high metastatic potential and upregulation of MAP4K4 with a MAP4K4 inhibitor to prevent metastasis while they wait for resection or radiation of the primary tumor would be of benefit." (PMID 31570734, 2019). "Moreover, high expression of MAP4K4 in lung adenocarcinoma is sufficient to activate the MAP kinase ERK for cancer growth and dissemination." (PMID 29796184, 2018). "Furthermore, MAP4K4 knockdown was found to induce apoptosis, cell cycle arrest, and inhibition of cell proliferation, migration and invasion in different cancer cells." (PMID 29970191, 2018). "MAP4K4 participate in the maintenance of malignant phenotype of many human cancers." (PMID 30429233, 2018). "Since small-molecule inhibitors of MAP4K4 are available, in order to eventually use these inhibitors in clinic, future studies should attempt to test their tumor prevention and antitumor activity in mouse models of cancer." (PMID 27800153, 2016). "However, none of these factors have been proved to be a direct phosphorylation substrate of MAP4K4 in cancer, implying that MAP4K4 regulates these factors or pathways indirectly." (PMID 27800153, 2016). "It is possible that MAP4K4 could promote tumor development and progression in certain types of cancer and functions as a tumor repressor in other types of cancer, or plays different roles at different stages during tumor development and progression." (PMID 27800153, 2016). "Negative association between MAP4K4 expression and patient prognosis has been observed in several types of human cancer." (PMID 27800153, 2016). "Given the potential role of MAP4K4 in cancer, we believe MAP4K4 inhibition may be a possible new direction in cancer therapy." (PMID 27800153, 2016). "Little information exists regarding how MAP4K4 is involved in cancer." (PMID 27800153, 2016). "This review summarizes our current understanding of MAP4K4 regulation and MAP4K4 in cancer." (PMID 27800153, 2016). "Together, current findings suggest that MAP4K4 may contribute to cancer mainly through canonical MAPK-independent mechanisms." (PMID 27800153, 2016). "We hope that this review article would advocate more basic and preclinical research on MAP4K4 in cancer, which could ultimately provide biological and mechanistic justifications for preclinical and clinical test of MAP4K4 inhibitor in cancer patients." (PMID 27800153, 2016). "Information regarding MAP4K4 in cancers is extremely limited, but increasing evidence suggests that MAP4K4 also plays an important role in cancer and MAP4K4 may represent a novel actionable cancer therapeutic target." (PMID 27800153, 2016). "Therefore it is crucial to gain a thorough understanding of how MAP4K4 is involved in a particular type of cancer functionally and mechanistically before conducting clinical testing of MAP4K4 inhibitor in cancer patients." (PMID 27800153, 2016). "Analogous to Theileria-induced host cell transformation, MAP4K4 signaling might be relevant in driving cancer cell dissemination in tumors, where increased levels of anti-cancer therapy-induced TNFα has been noted in the surrounding stroma." (PMID 24626571, 2014). "MAP4K4 was identified as a pro-migratory kinase in carcinoma cells." (PMID 24626571, 2014). "Additionally, c-JUN was found to regulate the expression of MMP1, a known mediator of cancer invasiveness, and MAP4K4, creating a feedback loop that may enhance metastatic potential." (PMID 39990663, 2025). "However, the functions of MAP4K4 in cancer are just beginning to be described and could be more diverse than current data indicate." (PMID 37223681, 2023). "Finally, we verified the high expression of MAP4K4 and its effect on promoting cancer." (PMID 36292671, 2022).
cancer (continued). "Besides its indispensable function in embryonic development, MAP4K4 plays a central role in systemic inflammation, lung inflammation, focal adhesion dynamic, insulin sensitivity, atherosclerosis, immunity, and cancer." (PMID 34511598, 2021). "Using the resulting Enrichment Scores (ES) derived from the MAP4K4 knockdown signature, we calculated information-theoretic measure, the Information Coefficient (IC) to examine genesets that best matched the MAP4K4 knockdown signature ES across these cancer cell lines." (PMID 31913126, 2020). "Notably, several miRNAs have been certified to regulate MAP4K4 expression in certain cancer." (PMID 29970191, 2018). "Other proteins are known inducers of epithelial to mesenchymal transition (EMT) (i.e. Laminins) or cancer cell spreading (i.e., CCN2, NPNT, WASF2, SERPINE, MAP4K4)." (PMID 40410902, 2025). "Targeting MAP4K4 with two well-known inhibitors, PF0626093314 and GNE-49526, improved the efficacy of radiotherapy in both radioresistant cancer cell lines." (PMID 38548749, 2024). "In summary, MAP4K4 and its role in regulating the JNK signalling pathway mediate many proliferation-related functions to promote cancer development." (PMID 36683274, 2023). "TNF-α has been reported to be a bona fide agonist of MAP4K4, and TNF-α is known to induce inflammation and cancer." (PMID 36292671, 2022). "During inflammatory tissue responses, MAP4K4 also promotes increased vascular permeability and leukocyte adhesion downstream of tumor necrosis factor alpha (TNFα) signaling, indicating a broader function of MAP4K4 in vascular biology that may contribute to pathogenesis and cancer." (PMID 36568222, 2022). "Functional analysis revealed that the upstream regulators (RICTOR, KDM5A, MAP4K4, and TRAP1) were activated due to the aberrant expression of sperm proteins in the cancer group compared to fertile men." (PMID 32942548, 2020). "Among them, MAP4K4, a serine/threonine kinase involved in activation of the JNK signaling pathway, was overexpressed in many types of human cancer and played an important role in proliferation, migration and invasiveness of cancer cells." (PMID 30710069, 2019). "MAP4K4 is TNFα-induced kinase, signaling through the JNK pathway and contributing to migration and metastasis of cancer cells." (PMID 24626571, 2014). "MAP4K4 (also known as HGK or NIK) is a serine/threonine kinase belonging to the Ste20 family of protein kinases, which plays a significant role in immunity, inflammation, metabolic disorders, cardiovascular diseases, and cancer." (PMID 39941781, 2025). "Although it is known that MAP4K4 functions through MAPK pathways, including JNK 1/2, ERK 1/2, and p38, it remains unclear which of the MAPK pathways is activated by MAP4K4 in cancer." (PMID 38548749, 2024). "Interesting, considering the role of ADAM10 in N-cadherin cleavage and the promigraion effector of N-cadherin in cancers, we proposed the hypothesis that ADAM10/N-cadherin might play a role in MAP4K4 mediated N-cadherin stability." (PMID 36922678, 2023). "Over the last few years, specific MAP4K4 inhibitors such as GNE-495 have been developed but have not yet been tested in cancer patients." (PMID 37223681, 2023). "Both MAP4K4 WT and kinase active mutant were able to restore the defective migration abilities of cancer cells, while kinase inactive mutant failed to rescue the defects." (PMID 36922678, 2023). "MAP4K4 phosphorylates TRAF2 in T cells, promoting its degradation; however, this has not been implicated in cancer." (PMID 34511598, 2021). "MAP4K4 also directly phosphorylates a pleckstrin domain-containing protein FARP1; however, the implication of this phosphorylation in cancer is unknown." (PMID 34511598, 2021). "Currently there is no sufficient information suggesting in which type of cancer MAP4K4 inhibitor can be used as a novel promising therapy." (PMID 27800153, 2016).
cancer (continued). "Besides MAPK/JNK, MAP4K4 has also been reported to regulate MAPK/ERK1/2 pathway and MAPK/p38 pathway in biological systems other than cancer." (PMID 27800153, 2016). "Evidence definitely linking MAP4K4 to the development and progression of any types of cancer is still lacking." (PMID 27800153, 2016). "MAP4K4 and its murine (Nck-interacting kinase), fly (misshapen) and worm (MIG15) orthologs are evolutionary conserved and control migration of both neurons and cancer cells." (PMID 25625039, 2015). "Thus, MAP4K4 couples growth factor signaling to actin cytoskeleton regulation in tumor cells, suggesting that MAP4K4 could present a promising novel target to be evaluated for treating growth factor-induced dissemination of MB tumors of different subgroups and of other human cancers." (PMID 25625039, 2015). "MAP4K4 implication in HGF-induced internalization of membrane transport proteins and drug transporters indicated a potential therapeutic benefit of targeting this function of MAP4K4 during chemotherapy, which remains one of the first-line treatments for cancer patients." (PMID 35296518, 2022). "Because MAP4K4 is ubiquitously expressed and MAP4K4 overexpression promotes cancer progression or metastasis, a systemic treatment using MAP4K4 agonists may not be feasible." (PMID 28061846, 2017). "No information is available about whether and how MAP4K4 is involved in resistance to standard cancer therapy." (PMID 27800153, 2016). "However, the role of MAP4K4 in collective migration of cancer cells has not been addressed." (PMID 37369604, 2023). "Although experimental evidence that supports the link between MAP4K4 and these pathways and cancer is currently not available, it is reasonable to believe that MAP4K4 could contribute to cancer through modulating these pathways or factors in a context-dependent manner." (PMID 27800153, 2016). "While several reports have shown that MAP4K4 and JNK are related to EMT in various cancers there is no data concerning the whole axis including both miRNAs." (PMID 31080555, 2019). "However, the interplay of MAP4K4 and the STRIPAK complex in cytoskeleton remodeling towards cancer cell dissemination has not been addressed and a direct substrate of MAP4K4 in this process has not yet been identified." (PMID 35941177, 2022).
tumor (53 papers, 2010 to 2025). "In other tumor types, MAP4K4 has been implicated in promoting tumor cell invasion and resistance in pancreatic cancer and melanoma through activation of the JNK and RhoA signaling pathways." (PMID 40486910, 2025). "Although MAP4K4 deficiency led to faster tumor development, it simultaneously reduced metastatic potential by impairing cell invasion, matrix remodeling and metastatic seeding." (PMID 41034525, 2025). "Intriguingly, among these 11 significantly associated genes, Lrp1, Abca1, Map4k4, Vegfa, and Nf1 regulate cell efferocytosis, micropinocytosis, and endocytic activities in DCs, macrophages, and tumor cells." (PMID 37508356, 2023). "It has been shown that MAP4K4 can control c-Met endocytosis and integrin-B1 activation, which are associated with invasive phenotypes in this tumor type." (PMID 37223681, 2023). "As discussed in this review, MAP4K4 signaling is dysregulated in many inflammatory diseases and malignancies and has been associated with tumor progression, metastasis, and poor prognosis." (PMID 37190200, 2023). "Treatment with MAP4K4 inhibitor GNE-495 reduced these tumor-promoting activities associated with MLK3 phosphorylation in vitro, and reduced tumor weight and MAP4K4 and MLK3 expression in vivo." (PMID 36568222, 2022). "MAP4K4 is associated with increased motility and reduced proliferation in tumor cells, but the regulation of this dichotomous functionality remained elusive." (PMID 35941177, 2022). "Conversely, MAP4K4 depletion decreased PM association of proteins involved in tumor immune evasion (CD155, CD276, and HLA-G), in solute influx regulation (CLIC1, SLCs, and ABCCs) and cell migration (CD155 and CD276)." (PMID 35296518, 2022). "We then more specifically discuss MAP4K4 functions associated with tumor growth and progression in the context of its dichotomous functionality as a promotor of invasion and repressor of tumor cell proliferation." (PMID 36568222, 2022). "MAP4K4 expression was also significantly associated with tumor size, TNM stage, lymph node metastasis and prognosis in PDAC patients." (PMID 29970191, 2018). "The influence of MAP4K4 on tumor proliferation, migration and invasion was associated with the activation of the c-jun N-terminal kinase (JNK) pathway." (PMID 28591712, 2017). "In addition, high levels of MAP4K4 have also been linked to poorer overall survival and higher tumor recurrence rates among patients with cancer." (PMID 38548749, 2024). "Tumour size and metastasis are also associated with MAP4K4 expression." (PMID 36683274, 2023). "Furthermore, our results show that high MAP4K4 expression is dramatically associated with aggressive tumor progression in patients with PCa, short overall survival time and short BCR-free survival time." (PMID 34112843, 2021). "In the context of targeting MAPK signaling, which is overexpressed in HCC and associated with tumor growth, the downregulation of mitogen-activated protein kinase kinase kinase kinase 4 (MAP4K4) using shRNA led to reduced cell proliferation, S-phase cell cycle blockade and increased tumor apoptosis." (PMID 32722054, 2020). "MAP4K4 expression is associated with tumor progression and metastasis in different solid tumors." (PMID 29796184, 2018). "Knockdown of MAP4K4 in H1975 cells caused significant reduction in tumor size." (PMID 28306189, 2017). "MAP4K4 is also known to promote tumour cell migration, invasion, and loss of adhesion." (PMID 24244164, 2013). "To elucidate the mechanism by which HMMR facilitates tumor metastasis, we conducted mRNA sequencing and mass spectrometry, identifying MAP4K4 as a key protein that interacts with and is regulated by HMMR." (PMID 39990663, 2025). "Group 1 corresponded to 14 pathways involved in the structural and functional organization of the extracellular matrix, cell–matrix interactions, and integrin-mediated adhesion, underscoring MAP4K4’s role in promoting aggressive tumor traits in MSI-GC." (PMID 39941781, 2025).